ILK (integrin linked kinase)
Diseases named in the same sentence as ILK in open-access papers (continued):
Sharing a sentence is not in itself a finding about the gene and the disease.
tumor (continued). "Therefore, deciphering whether and how the endothelial expression of ILK affects tumour growth and angiogenesis could support ILK as a target for anticancer therapies." (PMID 33573141, 2021). "However, the molecular basis for the high level expression and regulatory mechanism of ILK remain unclear in tumor." (PMID 27576342, 2016). "ILK-mediated pathway that may enhance tumor progression is its regulation on MMP expression." (PMID 15631637, 2005). "In conclusion, monitoring the activities of these inhibitors not only on tumor cell growth but also on T-cell activity will be indispensable when TTK and ILK inhibitors are proposed for chemotherapy." (PMID 40274929, 2025). "Furthermore, the C-terminus of CCDC25 interacts with integrin-linked kinase (ILK), which contributes to the recruitment of β-parvin, thus activating the β-parvin-RAC1-CDC42 cascade to facilitate the cytoskeleton rearrangement, and tumor cell proliferation and migration." (PMID 38023616, 2023). "In the presence of increased matrix stiffness, ILK regulates BCSC development via the PI3K/Akt pathway and promotes angiogenesis in tumor cells, ultimately contributing to tumor metastatic spread." (PMID 37916166, 2023). "In published studies, AGRN, ITGAV, FLNC, ILK, and RSU1 were overexpressed in HCC tumor tissues, thereby promoting tumor development, metastasis, and even leading to poor prognosis, which is consistent with our findings." (PMID 36110210, 2022). "ILK functions as an adapter protein through its kinase activity and regulates cell growth, EMT, invasion, migration, and tumor angiogenesis." (PMID 35379935, 2022). "PPAR-Riskscore was constructed by univariate Cox regression based on the expression of 4 genes (NR1D1, ILK, TNFRSF1A, and REN) in tumor tissues." (PMID 35481240, 2022). "In vivo, the combination reduced tumor burden, increased survival, and regulated EMT through the ILK/Akt/GSK3β/Slug pathway." (PMID 35804980, 2022). "Therefore, targeting ILK combined with TLRs stimulation and senescence induction could be a potentially synergetic approach to regulate senescence positively, stimulate innate immunity and ultimately suppress tumor growth." (PMID 34163519, 2021). "Animal results indicated that GTW, especially GTW+DDP, significantly reduced tumour burden, prolonged the life span of mice, and down-regulated the levels of tumour markers CA125 and HE4 by regulating EMT through the ILK/AKT/GSK3β/Slug signalling pathway." (PMID 33531984, 2021). "Silencing of the ILK gene induces apoptosis in SKOV-3 cells, blocks tumor growth in nude mouse xenografts." (PMID 35317111, 2021). "Both CM presented proteins involved in proliferation of both tumor and non-tumor cells, of which CAPN1, CST1, LAMC2 and RANBP3 stood out in CM3D and GPC6, ILK, MAPK1, MIF and PICALM in CM2D." (PMID 34884877, 2021). "We demonstrate a trend towards a reduced BCR-ABL1T315I+ tumor burden and significantly prolonged survival of mice with BCR-ABL1T315I+ CML treated with fibronectin or an ILK inhibitor in xenogeneic and syngeneic murine transplantation models, respectively." (PMID 32439895, 2020). "Within the tumor microenvironment (TME), ILK is activated in its phosphorylated form by focal adhesion kinase (FAK) and phosphatidylinositol 3-kinase (PI3-kinase)/Akt pathways." (PMID 32872127, 2020). "Knockdown of ILK in SKOV3 cells resulted in decreased cell proliferation and tumor growth, and inhibition of downstream kinase, AKT (protein kinase B)." (PMID 33256002, 2020). "Evidences suggested that both downregulated expression and inhibited kinase activity of ILK lead to attenuated phosphorylation of Ser473 and GSK-3β, resulting suppressed tumor growth and metastasis 14, 23-27." (PMID 31897228, 2020). "Control and ILK knockdown SKOV3 cells (clone 1 or virus 1) were implanted subcutaneously in NSG mice and tumor growth was monitored." (PMID 33256002, 2020).
tumor (continued). "Increased amounts of type I collagen correlate with integrins, switching to a high-affinity ligand-binding state, increasing FAK- and ILK-signaling activity, and promoting EMT in tumor pancreatic cells, for example." (PMID 32340328, 2020). "It has been shown that ILK can mediate activation of AKT and thereby play key role in tumor progression and metastasis interacting with cytoplasmic domain of integrin β1." (PMID 27563827, 2016). "ILK has important functions in promoting epithelial to mesenchymal transition (EMT) in mammary epithelium and the tumor invasion with a lower expression of E-cadherin." (PMID 27576342, 2016). "Mechanistically, ILK directly phosphorylates AKT on Ser473 and GSK-3β on Ser9 to mediate β-catenin translocation and regulate AP-1 expression for tumor cell proliferation." (PMID 25398317, 2014). "ILK was moderately, and activated FAK strongly, lost in all tumor cell lines in the presence of amygdalin." (PMID 25333694, 2014). "Former studies with this pharmacological inhibitor also demonstrated an effective reduction of ILK activity as well as a decrease of AKT (AKT kinase) and FAK (focal adhesion kinase) phosphorylation in tumor cell lines." (PMID 24386370, 2013). "Since HLE was unable to form tumor upon subcutaneous injection, only BEL7402 ILK knockdown stable clones were subjected to nude mice injection." (PMID 21347395, 2011). "Here we report a significant acceleration in tumor onset, development, and growth rate in MMTV-Wnt/ILK double-transgenic mice as well as a profound enhancement in pre-neoplastic mammary gland hyperplasia." (PMID 20565980, 2010). "ILK expression level plays one of the key roles in the biology of NSCLC and defines a more aggressive tumor phenotype of NSCLC." (PMID 15631637, 2005). "Conversely, expression of ILK+ cells was higher in tumor stroma, albeit not statistically significantly." (PMID 38727811, 2024). "Therefore, this study assessed the expression of FAK, ILK, CD44, HIF-1α, and Ki67 in EC patients after neoadjuvant radiochemotherapy followed by tumor resection (NRCHT+R) and correlated these markers with the MTE." (PMID 38727811, 2024). "Conversely, expression of ILK+ cells was higher in tumor stroma compared to tumor nests, albeit not statistically significantly." (PMID 38727811, 2024). "Based on immunofluorescence analyses of ILK+ and CD11b+ (myeloid) cells in both tumours and adjacent normal tissues, elevated expression of ILK was apparent not only in tumour epithelium but also in the tumour-infiltrating myeloid (CD11b+) cells." (PMID 38077324, 2023). "Furthermore, the role of ILK and its potential in tumorigenesis was investigated in the IOMM-Lee cell line, unveiling the regulatory effect of ILK on apoptosis, ECM, and tumor progression." (PMID 37887327, 2023). "By identifying the myeloid-specific ILK as a potential driver of CRC, our study reveals a mechanism through which the tumour-promoting roles of myeloid cells could be exploited for clinical applications." (PMID 38077324, 2023). "Subsequently, numerous studies have revealed that ILK plays a key role in epithelial-mesenchymal transition (EMT), invasion, and angiogenesis, suggesting that it could be an attractive target for tumor therapy." (PMID 36618074, 2022). "The negative correlations between ILK and tumor purity exhibited positive correlations with immune cell infiltration." (PMID 35692780, 2022). "Furthermore, we found that TMAO upregulates POSTN and activates the ILK/AKT/mTOR pathway, which induces tumor proliferation and migration." (PMID 35676936, 2022). "Moreover, the increased frequency of tumor-initiating cells is due, in part, to increased FLP stability, which is due to elevated ILK/cofilin signaling." (PMID 35804980, 2022). "The ability of ILK to regulate phosphorylation of components of the phosphoinositide 3-kinase/mammalian target of rapamycin (PI3K/mTOR) signaling complex, such as Akt and Rictor, is critical in promoting tumor cell survival." (PMID 35804980, 2022).
tumor (continued). "In pancreatic cancer xenografts, however, pharmacological ILK inhibition reduced tumour growth without affecting tumour angiogenesis." (PMID 33573141, 2021). "Therefore, pharmacological inhibition of ILK using a specific ILK inhibitor, QLT0267 potently inhibits YAP-dependent tumor growth in xenograft models." (PMID 32206112, 2020). "Interestingly, ILK has been shown to be involved in the development of BC stem-like cells (CSC), which are tumor-generating, having the capacity to produce tumors through stem cell self-renewal and differentiation." (PMID 33043811, 2020). "The staining of tumor tissue microarray serial sections for MT1-MMP revealed similar patterns of expression, with positive MT1-MMP immunoreactivity in approximately half of all tissues with positive ILK expression." (PMID 26959113, 2016). "Depletion of ILK also delayed tumor formation in sub-cutaneous ovarian cancer xenograft models; however intra-peritoneal tumor growth was not evaluated." (PMID 26959113, 2016). "Thus, the ability of ILK to downregulate Foxo3a expression, in conjunction with HIF-1α overexpression, plays a critical role in facilitating hypoxia-mediated tumor progression and metastasis." (PMID 25821081, 2015). "This indicated that ILK does not significantly regulate the behaviour of the tumour cells after transformation." (PMID 26349061, 2015). "Down-regulating ILK and FAK by amygdalin might therefore be a pivotal step in counteracting tumor dissemination." (PMID 25333694, 2014). "We evaluated the safety of ILK-treatment at four weeks after adenoviral delivery, especially in view of its propensity to induce angiogenesis and proliferation, but no neoplasia was detected in the liver, kidney or spleen of treated rats." (PMID 22348065, 2012). "No animal treated with ILK showed evidence of neoplasia in the liver, kidney or spleen up to the 9 week time point." (PMID 22348065, 2012). "When compared the overall ILK expression levels, ILK transcript level was significantly higher in tumor tissues than in non-tumorous liver (P = 0.004, unpaired t-test)." (PMID 21347395, 2011). "Several study revealed ILK was involved in cancer cell VEGF expression and tumor angiogenesis." (PMID 21949693, 2011). "Tumours that are positive for PTEN seem to have an alternative way of activating AKT and ERK, and the ILK pathway might well be that way." (PMID 20502457, 2010). "Lack of potent single-agent activity, when using in vivo tumor growth as an efficacy measure, lends support to the belief that ILK inhibitors must be developed in the context of other therapeutics." (PMID 19409087, 2009). "Peroxisome proliferator-activated receptor β-mediated activation of ILK and PDK1 is controlled at the transcriptional level and is closely connected to the decrease of PTEN expression, commonly lost in tumours, including those of ovarian origin." (PMID 18349831, 2008). "ILK was strongly expressed in 31% of tumor samples, whereas there was no ILK expression in noncancerous pulmonary tissue samples from the same patients, except for fibroblasts and infiltrating lymphocytes." (PMID 15631637, 2005). "It is worth adding that there were no measurable differences in the ILK protein expression between primary tumours with or without positive lymph nodes." (PMID 12771992, 2003). "While the elevated ILK expression in tumour epithelium compared to the adjacent normal tissue is supported by published reports, we observed higher tumour-infiltration of ILK-positive myeloid (CD11b+ ILK+) cells as indicated by merged images from both CD11b+ and ILK+ cells." (PMID 38077324, 2023). "However, a role for ILK in the tumor microenvironment (TME) and immune evasion has not been investigated." (PMID 35692780, 2022). "Finally, TLR stimulation could be an effective therapy combined with ILK inhibition and TIS for triggering cytotoxic immunity and regressing tumor growth." (PMID 34163519, 2021).
tumor (continued). "Therefore, ILK has numerous interactions with different cell signaling pathways and also mediates communications among these pathways, indicating its unique function and potential to be a therapeutic target and modulate the TME and suppress tumor growth." (PMID 34163519, 2021). "Indeed, several pro-proliferation proteins were uniquely identified in CM2D such as PICALM, which positively regulate cell proliferation and GPC6, MAPK1, ILK and MIF, all involved in cell proliferation, migration and invasion, including that of tumor cells, cardiomyocytes and endothelial cells." (PMID 34884877, 2021). "Interestingly, our observation on the human pathological specimens consistently revealed that RI and ILK negatively correlated in tumor and non-tumor tissues, which is corresponding to in vitro and animal experiments." (PMID 27576342, 2016). "Recently, the interaction of metastatic tumor cells with their surrounding ECM was shown to be mediated by filopodium-like protrusions containing β1 integrin, with formation of these structures under control of cytoskeleton-regulatory proteins such as ILK/β-parvin and cofillin." (PMID 25606594, 2014). "ILK overexpression was neither correlated with tumor grade nor patient survival." (PMID 21347395, 2011). "Thus, it appears that ILK is more likely to regulate GSK3β activity directly in vivo, and dysregulation of this nexus, rather than PKB, might have an important role in epithelial-derived tumour growth and survival." (PMID 12771992, 2003). "Quantitative PCR was used to examine the transcript level of ILK in 57 paired HCC tumor samples, each of which consisted of the tumor (T) tissue and the adjacent non-tumorous (NT) liver." (PMID 21347395, 2011).
infection (17 papers, 2013 to 2025). The state of being infected such as from the introduction of a foreign agent such as serum, vaccine, antigenic substance or organism. "Transcriptomic analyses of RVFV-infected cells further reinforced the impact of infection on the expression of cytoskeleton- and adhesion-related genes, including the integrin-linked kinase (ILK) pathway." (PMID 41157666, 2025). "Other pathways that demonstrated differential regulation by infection included integrin-linked kinase (ILK), integrin-, ephrin B-, and ephrin receptor-signaling as well as remodeling of epithelial adherens junctions." (PMID 33750985, 2021). "In that study, the top pathways altered in response to infection with both RVFV strains included the regulation of the antiviral response, mitochondrial dysfunction, the DNA damage response, and integrin-linked kinase (ILK) signaling." (PMID 37306574, 2023). "This suggests that EspO1 inhibits cell detachment during infection in a HAX-1-dependent/ILK independent manner, while NleH1 and NleF operate independently of HAX-1." (PMID 34021690, 2021). "Both HAX-1 and ILK were further confirmed as EspO1-interacting proteins during infection using T3SS-delivered EspO1." (PMID 34021690, 2021). "While Compound 22 showed efficacy in decreasing RVFV replication, the mechanism by which ILK facilitates infection remains to be seen." (PMID 29085037, 2017). "Because of difficulty of isolating enough NCCs from NKO mutant embryos, we established an ILKf/f NCC culture and ablated ILK expression in vitro by infection of Cre recombinase adenoviruses." (PMID 24131868, 2013). "ILK influences the host response to C. rodentium -induced infection, independently of reduced colonization in the ILK knockout mice." (PMID 24024606, 2013). "In contrast, in the immunocompetent neonatal mice, DENV replicates in the brains, induces neurological symptoms, such as seizure and paralysis, and results in death after infection, which makes it a feasible model for us to test the efficacy of blocking ILK as a therapeutic strategy." (PMID 36930690, 2023). "Besides DENV, ILK has also been shown to support the infection of coxsackievirus B3 and the hepatitis C virus." (PMID 36930690, 2023). "Therefore, proliferation and apoptosis in A549 cells undergoing ILK RNAi infection and 10% CDDP treatment was evaluated." (PMID 25760437, 2015). "In order to elucidate whether lentivirus-mediated ILK RNAi had any effects on the cell cycle of A549 cells, all three groups of A549 cells were subjected to a flow cytometry assay after 3 days of infection." (PMID 25760437, 2015). "Also, given that Compound 22 was only present on the cells for one hour prior to infection, this may indicate that ILK signaling used for entry or early events in the viral replication cycle." (PMID 29085037, 2017). "If the density of ILK on cells constitutively expressing HIV-1 protein and A2 levels is only ∼10 copies, it follows that in the setting of natural infection, presentation of ILK on the cell surface would be even lower." (PMID 35394875, 2022). "To determine if the ILK inhibitor suppresses TRIM28 phosphorylation and HSV-1 replication, we treated HSV-1-infected SN-K-SH cells with OSU-T315 after 1 hour of infection." (PMID 35350437, 2022). "Other pathways were altered in both MP12 and ZH548 infection, including G2/M DNA damage checkpoint, ATM signaling, mitochondrial dysfunction, role of PKR in interferon induction and antiviral response, and ILK signaling." (PMID 29085037, 2017). "We observed a complete reversal in the canonical pathways, including ILK and FAK signaling as well as upstream regulators, further corroborating that testicular injury-related transcriptomic alterations resolve within 4 weeks of infection." (PMID 39775442, 2025). "Nonetheless, there was no increase in the cleaved caspase-3 levels in ILK knockdown cells after infection." (PMID 36930690, 2023).
infection (continued). "After 24 hours of infection, the levels of Akt Ser473 were increased in control cells and ILK knockdown cells without or with ectopic expression of ILK." (PMID 35350437, 2022). "After 45 min of infection, we found that comparable virus genomes were detected in the control and ILK knockdown cells, showing that ILK fails to affect HSV-1 entry." (PMID 35350437, 2022). "In ILK knockdown cells, the ILK E359K mutant failed to affect Akt activation before infection and abrogated Akt activation after 24 hours of infection." (PMID 35350437, 2022).
heart disease (9 papers, 2011 to 2025). "Integrin-linked kinase (ILK) has been proposed as a novel molecular target that has translational potential in diverse cardiac diseases, since its upregulation promotes a broadly cardioprotective phenotype." (PMID 24260102, 2013). "Additionally, the interaction of LAMA4 with ILK, another protein implicated in cardiac disease, suggests a complex network of protein interactions that are vital for maintaining the structural and functional integrity of the heart." (PMID 39337275, 2024). "ILK is highly expressed in cardiac muscle, where it plays a key role in cell migration and the progression of cardiac diseases related to integrin function." (PMID 40141387, 2025). "Experimental models further underscored the therapeutic potential of ILK in treating heart diseases." (PMID 39337275, 2024). "The highly cited literature also reported the role of thymosin β4 on ILK and the resulting mediated protective effects against ischaemic heart disease." (PMID 38699584, 2024). "ILK is highly expressed in cardiac muscle, where it plays a critical role in cell migration and development of cardiac diseases related to integrin function." (PMID 31434946, 2019). "ILK-regulated signaling is an adaptive hypertrophic response mechanism related to multiple clinical heart diseases." (PMID 28692647, 2017). "Since ILK is known to be activated by hypoxia, which normally occurs during fetal heart development and in postnatal heart disease, these findings support the paradigm that stress induction of ILK might serve as a novel endogenous regulator of cardiomyogenesis." (PMID 22666394, 2012). "Since α-Parvin/ILK/PINCH-1 is known as a major signaling platform within the integrin-actin network, our results suggest a possibility that PIP manipulation may lead to novel targets for heart disease." (PMID 21625516, 2011).